MPHOSPH6 (M-phase phosphoprotein 6)
Description:
RNA-binding protein that associates with the RNA exosome complex. Involved in the 3'-processing of the 7S pre-RNA to the mature 5.8S rRNA and play a role in recruiting the RNA exosome complex to pre-rRNA; this function may include C1D.
Synonyms: MPP6; MPP; MPP-6
Tractability: Small molecule: a structure with a bound ligand is known. PROTAC: UniProt records ubiquitination sites on it; ubiquitination databases record sites on it; its protein half-life has been measured.
Gene: Protein-coding gene on chromosome 16 (82,147,798 to 82,170,228, reverse strand). Ensembl gene ENSG00000135698.
Subcellular location: Nucleus, nucleolus; Cytoplasm
Subcellular location (Human Protein Atlas): Nucleoli; Nucleoplasm
Pathways (Reactome):
Metabolism of RNA: Major pathway of rRNA processing in the nucleolus and cytosol; Nuclear RNA decay
Gene Ontology:
Molecular function: protein binding
Biological process: maturation of 5.8S rRNA
Cellular component: exosome (RNase complex); nuclear exosome (RNase complex); nucleolus; nucleus; nucleoplasm; cytoplasm
Genetic constraint (gnomAD): Loss-of-function variants: 20 observed, 18.08 expected, observed/expected ratio (o/e) 1.11, 90% interval 0.78 to 1.6. The synonymous counts are far from expectation, so gnomAD's model fits this gene poorly and the ratio says little. Missense variants: 253 observed, 173.05 expected, observed/expected ratio (o/e) 1.46, 90% interval 1.32 to 1.62. Synonymous variants: 81 observed, 54.66 expected, observed/expected ratio (o/e) 1.48, 90% interval 1.24 to 1.78.
Homologues: Orthologues: chimpanzee MPHOSPH6 (99% identical), macaque MPHOSPH6 (99% identical), guinea pig Mphosph6 (94% identical), dog MPHOSPH6 (92% identical), mouse Mphosph6 (88% identical), rat Mphosph6 (82% identical), rat LOC134479438 (77% identical), tropical clawed frog mphosph6 (72% identical), zebrafish mphosph6 (62% identical), Caenorhabditis elegans F29A7.6 (32% identical).
Diseases named in the same sentence as MPHOSPH6 in open-access papers:
MPHOSPH6 is named in the same sentence as 11 diseases in open-access papers, as found by Europe PMC text mining. Sharing a sentence is not in itself a finding about the gene and the disease. The quoted sentences say what the papers report.
coronary artery disease (2 papers, 2017 to 2024). "The rs11125529, rs7675998, rs8105767, and rs7194734 SNPs belong to the ACYP2, NAF1, ZNF208, and MPHOSPH6 genes, respectively, which were found to be associated with increasing risk of developing coronary heart disease." (PMID 38293941, 2024).
lung adenocarcinoma (1 paper, 2023). A carcinoma that arises from the lung and is characterized by the presence of malignant glandular epithelial cells. "Of the 144 LTL genetic instruments, 12 colocalised with lung adenocarcinoma risk and revealed novel susceptibility loci, including MPHOSPH6, PRPF6, and POLI." (PMID 37079368, 2023).
lung carcinoma (1 paper, 2023). "The lung cancer risk allele of the MPHOSPH6 sentinel variant (rs2303262) was associated with longer LTL, reduced pulmonary function, and increased MPHOSPH6 gene expression in lung tissue." (PMID 37079368, 2023). "Several colocalised loci mapped to genes that have not been previously linked to lung cancer risk at genome-wide significant level: MPHOSPH6 (16q23.3; rs2303262), PRPF6 (20q13.33; rs80150989), and POLI (18q21.2; rs2276182)." (PMID 37079368, 2023).
psoriasis (1 paper, 2026). An autoimmune condition characterized by red, well-delineated plaques with silvery scales that are usually on the extensor surfaces and scalp. "Machine learning pinpointed MPHOSPH6, ENO1, MKI67, and FABP5 as lactylation-related biomarkers for psoriasis, with ROC curves confirming their strong diagnostic capabilities." (PMID 41909697, 2026).
schizophrenia (1 paper, 2016). A major psychotic disorder characterized by abnormalities in the perception or expression of reality. "MPHOSPH6 is related to the pathways in Sertoli-Sertoli Cell Junction Dynamics and Deadenylation-dependent mRNA decay; it is in a RNA exosome complex and is genomewide associated with SNP clusters in schizophrenia." (PMID 28117656, 2016).
MPHOSPH6 also shares sentences with these, for which no sentence is quoted: breast carcinoma (1 paper); colorectal cancer (1); hepatocellular carcinoma (1); IgA nephropathy (1); respiratory disease (1); type 2 diabetes (1).